MIB1 (MIB E3 ubiquitin protein ligase 1)
Diseases named in the same sentence as MIB1 in open-access papers (continued):
Sharing a sentence is not in itself a finding about the gene and the disease.
sarcoma (1 paper, 2011). A usually aggressive malignant neoplasm of the soft tissue or bone.
sarcopenia (1 paper, 2021). Progressive decline in muscle mass due to aging which results in decreased functional capacity of muscles. "Collectively, our finding suggests the importance of the Mib1–Actn3 axis in the skeletal muscle maintenance with age and unravels one of mechanisms implicated in the cause of sarcopenia." (PMID 33637766, 2021). "In that, further studies on the implications of sex hormones and Mib1 in sarcopenia using pharmacologically or genetically modified mice are required to reveal the putative correlation between sex hormones and Mib1 with age." (PMID 33637766, 2021).
serous carcinoma (1 paper, 2014).
spinal muscular atrophy (1 paper, 2021). A motor neuron disease that affect the muscles, and characterized by muscle weakness and atrophy resulting from progressive degeneration and irreversible loss of the anterior horn cells in the spinal cord (i.e., lower motor neurons) and the brain stem nuclei. "Additionally, MIB1 has been implicated in the pathogenesis of spinal muscular atrophy by regulating cellular senescence and degrading motor neuron) and Werner syndrome protein." (PMID 33793053, 2021).
testicular germ cell tumor (1 paper, 2020). A germ cell tumor arising from the testis. "Other biomarkers have been studied for their prognostic/predictive value in testicular germ cell tumors, including MIB-1, CXCL12, CXCR4 and beta-catenin." (PMID 32758242, 2020). "The role of MIB-1 scoring as a prognostic marker in testicular germ cell tumors has been debatable, also because of different methodologies and cutoffs used in its assessment." (PMID 32758242, 2020).
toxoplasmosis (1 paper, 2015). A parasitic disease contracted by the ingestion or fetal transmission of toxoplasma gondii. "Immunohistochemistry was initially performed for glial fibrillary acidic protein (GFAP), MIB-1, CD45, CD68, CMV, and toxoplasmosis antigen." (PMID 26328586, 2015). "MIB-1 was positive in approximately 50 % of the atypical cells, while stains for CMV and toxoplasmosis were negative." (PMID 26328586, 2015).
ZIKV infection (1 paper, 2022). "Therefore, we hypothesize that ZIKV infection induces Mib1-mediated proteasomal activity to degrade PCM1 and Cx43 and damage the gap junction, and also impairs lamin A, hence impairing syncytia function of cardiomyocytes." (PMID 36226984, 2022).
tumor (269 papers, 1995 to 2026). "According to the WHO CNS5 2021 criteria, high mitotic index, high Mib1 proliferative index, vascular proliferation and tumor necrosis were strongly linked to O3 as observed in our study." (PMID 40315229, 2025). "Knockdown of mib1 dramatically suppressed the tumor overgrowth and invasive migration caused by ykiS168A/Toll-6ACT (H and EV6F) and QykiACT/scrib−/− (Fig. EV6G–I)." (PMID 40551010, 2025). "Only the relative MIB-1 LI (ratio between post- and pre-treatment MIB-1 LI) was associated with the tumor response (p = 0.005)." (PMID 40647527, 2025). "For this purpose, a potential association of MIB-1 LI values and pre- and postoperative tumor growth behavior has been analyzed including all potential cofounding factors." (PMID 38580878, 2024). "No histologic prognosticator is specific to the insula and most, including vimentin staining and MIB-1/Ki-67 PI, owe their prognostic effect to their association with tumor grade." (PMID 37619597, 2024). "Primary site (p < 0.0001), larger tumor size (p = 0.0153), higher mitotic figure (p < 0.0001), higher modified Fletcher classification (0 < 0.0001) and higher MIB-1 index (p < 0.0001) were significantly associated with poor prognosis." (PMID 38191907, 2024). "High MIB1 proliferation index was associated with poor TIL density in the invading tumor front (p = 0.006, r = 0.47) and in inner tumor areas (p = 0.02, r = 0.40)." (PMID 36586079, 2023). "TIL density in inner stroma was inversely linked to local invasion (marginal p = 0.05), tumor budding (TB) (p = 0.005), MIB1 (p = 0.02), and HIF1α expression (p = 0.02)." (PMID 36586079, 2023). "An expression of the proliferative marker MIB1 reaching 4.6% or beyond was associated with a higher rate of tumor recurrences (17.3% compared to 43.8%, p < 0.0001)." (PMID 35838837, 2023). "They demonstrated that MIB-1 labeling index > 30% is strongly associated with an increased risk of tumor progression and death in this mentioned study." (PMID 35453901, 2022). "Male sex, low plasma fibrinogen levels and diffuse CD68+ macrophage infiltrates were found to be significantly associated with an increase in the MIB-1 labeling index in recurrent tumor tissue samples." (PMID 35453901, 2022). "An increased MIB-1 labeling index is considered a molecular marker for aggressive tumor biology, which implies an increased risk for invasive growth and shortened time to tumor progression in PAs." (PMID 36498723, 2022). "Higher MIB1 expression was associated with smaller tumors (p = 0.0149) but with increased radiographic tumor growth (p = 0.0003)." (PMID 33641674, 2021). "In our univariate analysis, tumor size was also significantly associated with higher MIB-1 labeling indices." (PMID 34298854, 2021). "We, therefore, used the relative increase (percent) in tumor volume per year, which showed a significant association with the expression of the proliferation marker MIB1." (PMID 33530441, 2021). "They found that peritumoral edema is significantly associated with a higher MIB-1 labeling index and the tumor size." (PMID 34298854, 2021). "An immunopositivity of 1.03% or more of the tumor cells for the proliferation marker MIB1 was also associated with a higher rate of COX2 expression (OR 2.66 (1.94–3.67, p < 0.0001)." (PMID 31291992, 2019). "Immunohistochemistry for the common IDH (isocitrate dehydrogenase) mutation in IDH mutated tumors and MIB-1 (monoclonal antibody to Ki67) staining in IDH wild-type tumors would be more sensitive to low levels of tumor infiltration." (PMID 30765763, 2019). "To further analyze the underlying processes of tumor inhibition, we stained formalin fixed paraffin embedded sections of the tumors for markers of proliferation (Ki-67/mib-1) and apoptosis (cleaved caspase-3)." (PMID 31664117, 2019). "Among the BCs with cNHERF1 overexpression, 67.1% exhibited a significant association with tumor size > 2 cm (p = 0.023) and 68.4% with MIB1 positive expression (p = 0.027)." (PMID 29716631, 2018).
tumor (continued). "Supporting its association with good prognosis, tumour DACH 1 expression correlated with low cell proliferation (MIB1)." (PMID 24392136, 2014). "Statistical analysis showed a strong association between the MIB1 labelling index and histological grade (P < 0.001), tumour size (P = 0.002), tumour type (P < 0.001) and also patient survival (P < 0.001)." (PMID 7819031, 1995). "Univariate Cox proportional hazards analysis revealed that NF2 alteration/22q loss (hazard ratio [HR], 16.8; 95% confidence interval [CI], 2.1–137.0; p = 0.009) and MIB-1 LI > 4 (HR, 4.2; 95% CI, 1.05–16.9; p = 0.04) were significantly associated with tumor recurrence." (PMID 35804955, 2022). "The additional assessment of MIB-1 regarding tumor recurrence risk could improve stratification of patients to specific follow-up." (PMID 36230518, 2022). "Our results suggest that patients with an elevated MIB-1 index and nuclear atypia on pathologic analysis, posterior fossa location of their tumor, and STR are at higher risk for recurrence and should be considered for closer follow-up or even adjuvant radiotherapy." (PMID 32983999, 2020). "Positive cytology and adhesions were, in many studies, strongly connected with the tumour’s metastatic potential, and with a particular molecular arrangement, in particular loss of e-cadherin, positive of mib-1 and p-53, aneuploidy of DNA and mitotic activity index (MAI)." (PMID 23781280, 2013). "Alterations observed in the G1-S checkpoint of H/RS cell cycle, in the principal tumor suppressor pathways Rb-p16INK4a and p27KIP1, and the high rate of proliferation (MIB1, BCL6) are also strongly associated with higher infiltration of the overall immune response against the tumor." (PMID 22927872, 2012). "MIB-1, which recognises a nuclear antigen (Ki-67) associated with all phases of the cell cycle except in resting cells, is overexpressed in several human tumours and is commonly considered very useful in the evaluation of tumour cell growth." (PMID 12085205, 2002). "Taken together, clinical and especially biological prognostic factors like MIB-1 could help identify patients with a high risk of tumor relapse who might benefit from early and intensified adjuvant radiotherapy as well as from dose escalation of macroscopic tumor tissue." (PMID 34172069, 2021). "Therefore, the MIB-1 with association with other molecular parameters mightreflect tumor behavior and POF in patients with GB." (PMID 22734595, 2012). "MIB1-positive tumor cell (%MIB1 LI.T) and endothelial cell (%MIB1 LI.E) percentages were substantially correlated (p = 0.01)." (PMID 41614857, 2025). "Mechanistically, Spz5 binds to tumor cell Toll-6 receptors, triggering the degradation of the endocytic adaptor protein AP-2α via Mib1-mediated ubiquitination." (PMID 40551010, 2025). "QuPath_DIA measured hormone-dependent MIB1 nuclear expression in tumor and stromal endothelial cells." (PMID 41614857, 2025). "Only PRL-secreting PitNETs showed a significant correlation between VEGF protein levels, PRL expression, and MIB1 LI-positive tumor cells." (PMID 41614857, 2025). "The MIB-1 labeling index, which reflects proliferative activity by measuring Ki-67 expression during the cell cycle, is an established prognostic marker for tumor growth, survival and local PFS in various CNS tumors." (PMID 41382243, 2025). "There was also a higher prevalence of Mib1/Ki‐67 > 20% in cases compared to controls, as well as G3 grading, possibly reflecting higher cell proliferation and, thus, greater intrinsic tumor aggressiveness among these patients." (PMID 40247778, 2025).
tumor (continued). "In this study, adjuvant radiotherapy was recommended for patients with a high likelihood of recurrence, such as a high MIB1 index, whereas salvage therapy was selected as a treatment strategy for those who experience tumor progression." (PMID 38618419, 2024). "In our case, the tumor was 17.5cm with 1-2 mitotic figures/10 hpf, focal areas of necrosis, hemorrhage, and MiB1/Ki67 was 10-12%." (PMID 39021462, 2024). "Our data show that the SUV correlates with the proliferative index marker MIB-1 (Ki-67) and a large tumor volume—two factors that are prognostic for the presence of malignancy in other studies." (PMID 39594712, 2024). "To investigate the functional association of the IGF2BP3/MIB1/FTO loop with IGF2BP3-induced NETosis and tumor survival, we disrupted the pathway using a genetic approach." (PMID 38167409, 2024). "A linear regression was run to understand the relationship between preoperative tumor volume and MIB1-proliferation rate in all tumors." (PMID 39594712, 2024). "Preoperative tumor volume (mean 211.2 ± 434.7, 1.2–2294.3 cm3) statistically significantly predicted the maximum MIB-1 proliferation rate (mean 30 ± 23, 3–80%); F (1.26) = 4.888; p = 0.036." (PMID 39594712, 2024). "The tumor cell ability to proliferate can be determined by the biomarker Ki-67/MIB-1 and the high level of this biomarker is related to metastasis in numerous malignancies." (PMID 39868448, 2024). "In terms of immunohistochemistry (IHC), these tumor cells show a characteristic cell membrane‐positive reaction for MIB‐1." (PMID 39447085, 2024). "FOXP3+ TILs infiltration and FOXP3+/CD8+ ratios were higher in inner tumor areas, linked with LDH5 expression, and higher MIB1 proliferation index (p = 0.03) and SMA expression (p = 0.001)." (PMID 36900270, 2023). "Nuclear proliferation marker MIB-1 (Ki-67) immunohistochemistry (IHC) is used to examine tumor cell proliferation." (PMID 37970922, 2023). "The median proportion of MIB1-positive tumor cells in micrometastases was 0% (range, 0%-3%); furthermore, no mitotic figures were seen in the smaller micrometastases." (PMID 37052618, 2023). "We performed qRT‐PCR, western blotting, and immunohistochemistry (IHC) assays to confirm SNORA73B expression and MIB1 levels in the xenograft tumour tissues." (PMID 37488742, 2023). "The results showed that SNORA73B expression and MIB1 levels were considerably higher in the xenograft tumour tissues of the SNORA73B group than that of the vector group." (PMID 37488742, 2023). "TIL density in the invading tumor front was inversely related with lymph node involvement (p = 0.03), HIF1α expression (p = 0.008), vessel density (p = 0.02), and MIB1 (p = 0.006)." (PMID 36586079, 2023). "Immunohistochemical staining (IHC) of the nuclear proliferation marker MIB-1 (Ki-67) is extensively used to evaluate tumor cell proliferation and growth." (PMID 37970922, 2023). "Immunohistochemically, the tumor cells stained diffusely positive for S100 protein and SOX10, indicating Schwann cell differentiation, and MIB1-positive cells showed an increase of up to 10% in the tumor center." (PMID 39516973, 2023). "In particular, we assessed the relationship between the immunohistochemical expression of IGFBP6 and MIB-1, a widely used marker of the tumor proliferative activity, and found a positive correlation between these two markers." (PMID 35654889, 2023). "Because a higher MIB-1 index was significantly associated with a higher recurrence rate, the authors deduced that the MAC-score was also a predictor of tumor progression and recurrence rate." (PMID 36523995, 2022). "Ki-67/MIB-1 proliferating index is mentioned for many tumours and appears as a useful biomarker in grading and prognostications; however differences in techniques and determination make it problematic to establish reliable cutoff values." (PMID 35879477, 2022).
tumor (continued). "MIB1 proliferation index was significantly higher in tumors with a high CD68Mφ-score, especially in inner tumor areas (11/35 vs. 8/63; p = 0.02)." (PMID 35406573, 2022). "One RPA patient with multiple recurrent events showed increasing MIB-1 expression in every subsequent recurrent tumor." (PMID 35637257, 2022). "The results obtained by the authors showed that Ki-67/MIB-1 is significantly higher in the areas of the tumor showing PpIX fluorescence (20% vs. 10%)." (PMID 35055109, 2022). "MIB-1 and MC are already known predictors for tumor recurrence, but only MC is integrated in the current classification." (PMID 36230518, 2022). "The mean time to tumor progression in those cases with an increased MIB-1 labeling index (≥5%) was 39.6 (95% CI: 12.7–66.4) months, whereas those with an MIB-1 labeling index <5% had a mean time to tumor progression of 77.6 (95% CI: 67.5–87.8) months." (PMID 35877258, 2022). "The mean SIRPαMφ-score in inner tumor areas was 0.69, 0.71, and 0.94 in tumors with low, medium, and high MIB1 proliferation index, respectively (p > 0.12)." (PMID 35406573, 2022). "In the multivariate analysis only MIB1 expression was an independent significant factor regarding tumor growth (p = 0.0002)." (PMID 33641674, 2021). "In those patients who had a tumor recurrence of their SM in the present series, highly increased MIB-1 labeling indices were observed." (PMID 34277695, 2021). "The median of proliferation marker MIB-1 was assessed as a prognostic factor for local progression and new distant tumor lesions." (PMID 34172069, 2021). "Tumors with a MIB1 expression below 1.4% had a larger preoperative tumor size compared to tumors with a higher MIB1 expression exceeding or equal 1.4% (5.13 compared to 4.03 cm3, p = 0.0188)." (PMID 33530441, 2021). "A MIB1 expression exceeding the cutoff at 1.4% had a significantly faster percentual volumetric tumor growth when compared to tumors with lower MIB1 expression (4.53 and 3.05%/year, respectively, p = 0.0005)." (PMID 33530441, 2021). "A MIB1 expression exceeding 1.4% was revealed as an independent factor for faster tumor growth p = 0.0008)." (PMID 33530441, 2021). "In our cohort, we found a trend-level significant correlation between recurrence of tumor and a high MIB-1 index as a tumor-specific biological factor." (PMID 34172069, 2021). "In those patients with tumor recurrence of the SM, highly increased MIB-1 (≥5%) labeling indices were observed." (PMID 34277695, 2021). "In contrast to MIB1, a higher preoperative tumor volume was seen for higher expression scores for all lymphocyte and macrophage markers, regarding the overall score and the CART-derived cutoffs." (PMID 33530441, 2021). "To determine the impact of MIB1 knockdown on pancreatic cell growth in vivo, we subcutaneously injected BxPC‐3 cells (expressing shControl or shMIB1#1) in nude mice and assessed tumor growth." (PMID 33793053, 2021). "Clinical parameters and results of the immunohistochemical expression of COX2 and MIB1 in resected tumor tissue samples were obtained from our prior study." (PMID 33641674, 2021). "The tumor tissue showed high expression levels of Mib-1 indicating a high proliferation rate as well as S-100 pointing towards a neuroectodermal origin of the tumor cells." (PMID 34412684, 2021). "A result that is harder to grasp, is the preoperative tumor volume according to our MIB1 expression results." (PMID 33641674, 2021). "Cases with a MIB1 expression < 1.4% had a larger tumor volume than tumors with a proliferative marker expression of 1.4% or higher (5.16 compared to 3.99 cm3, p = 0.0149)." (PMID 33641674, 2021). "Although, the expression of MIB1 has been analyzed in this study indirectly by the inclusion of the WHO grade of each tumor, a detailed analysis of the correlation of MIB1 expression and invasive growth in future studies would be of great interest." (PMID 33287241, 2020).